NRAS (NRAS proto-oncogene, GTPase)
Diseases named in the same sentence as NRAS in open-access papers (continued):
Sharing a sentence is not in itself a finding about the gene and the disease.
metastatic melanoma (continued). "However, subjects with metastatic NRAS mutated tumors had significantly lower ERα (p<0.01) and ERβ (p<0.01) expressions compared to the total population of subjects with metastatic melanoma." (PMID 35371312, 2022). "This study aimed to determine whether the detection of ctDNA, based on the rapid identification of common BRAF and NRAS mutations before systemic treatment initiation, was associated with the prognosis of metastatic melanoma, in an intention-to-treat setting." (PMID 32664549, 2020). "The purpose of this study was to determine whether the detection of ctDNA, based on the identification of BRAF and NRAS mutations before systemic treatment initiation, was associated with the prognosis of metastatic melanoma." (PMID 32664549, 2020). "This pathway describes the molecular events known to occur during the transition from normal melanocyte to metastatic melanoma, including oncogenic NRAS and BRAF mutations, which activate Raf-MEK-ERK and PI3K-Akt, leading to increased cellular proliferation and cell survival." (PMID 30721246, 2019). "Furthermore, BRAF and NRAS mutations were confirmed to be mutually exclusive, with a good consistency in mutation distribution between primary and metastatic melanoma lesions." (PMID 29492214, 2018). "In addition to BRAF mutations, metastatic melanoma frequently harbors activating NRAS mutations (15%–28%) for which MEK inhibitor therapy has shown early clinical activity." (PMID 28147313, 2017). "Similarly, previous studies have shown that mutations in the NRAS gene, which lead to a constantly active NRAS protein, are found in approximately ~13–25% of metastatic melanoma patients." (PMID 28900470, 2017). "The NRAS mutation was reported as an independent prognostic factor in metastatic melanoma." (PMID 27213536, 2016). "CTC populations decreased in patients after receiving immunotherapy for BRAF, NRAS, and KIT mutant alleles in metastatic melanoma, highlighting the utility of monitoring CTC response to treatment to identify BRAF-mutant non-responders." (PMID 39156972, 2024). "In metastatic melanoma patients, ctDNA detection promotes the identification of typical mutations (i.e., BRAF and Neuroblastoma RAS Viral Oncogene Homolog (NRAS)) and epigenetic markers such as methylated DNA." (PMID 36835424, 2023). "Conversely to our TCGA analysis, the BRAF-mutated A375M showed an elevated expression of ERα, thus representing a model of metastatic melanoma, opposite to the NRAS ones in our study." (PMID 35371312, 2022). "In particular, several studies conducted on metastatic melanoma patients have highlighted the utility of liquid biopsy in detecting and monitoring BRAF/NRAS mutations through the use of different technologies." (PMID 35804825, 2022). "We demonstrate strong enrichment of ecDNA molecules containing EGFR, FGFR2 and MYC from human cancer cells and NRAS ecDNA from human metastatic melanoma with acquired therapeutic resistance." (PMID 36253572, 2022). "In one study, 73% of 48 patients with metastatic melanoma had tumor-associated BRAF and NRAS alterations in ctDNA analysis." (PMID 32010431, 2020). "The phase III NEMO study observed a similar PFS improvement with the MEK inhibitor binimetinib versus DTIC (HR 0.62; p < 0.001) in treatment-naïve or immunotherapy-pretreated patients with NRAS-mutant metastatic melanoma." (PMID 32610581, 2020). "An autopsy cohort of 50 patients with BRAF- and NRAS-mutant cutaneous metastatic melanomas including 139 visceral metastases was analysed for mutant allele fractions (MAF), determined by pyrosequencing and corrected for tumor/normal ratio." (PMID 31391014, 2019).
metastatic melanoma (continued). "Treatment of metastatic melanoma targeting genetically activated oncogene pathways (BRAF/NRAS/KIT pathways) and so-called immune-checkpoints have significantly improved overall survival rates of metastatic melanoma patients in recent years." (PMID 29614062, 2018). "In this monocentric prospective study, samples from 19 patients with stage IV metastatic melanoma collected before and after treatment were assessed for BRAF and NRAS mutations." (PMID 30546839, 2018). "Protein expression in a cohort of 32 drug naïve BRAF/NRAS metastatic melanoma specimens was examined." (PMID 30116025, 2018). "In conclusion, we demonstrated that the detection of the BRAF and NRAS cfDNA status with the IdyllaTM assay is feasible in a routine manner in a pathology laboratory, before and after systemic treatment of patients with metastatic melanoma." (PMID 30546839, 2018). "Altogether, these results suggest that Usp9x overexpression is an early event in expansion of primary and metastatic melanoma, involving stabilization of Ets-1 to amplify NRAS expression." (PMID 28198367, 2017). "The determination of NRAS and BRAF mutation status is a major requirement in the treatment of patients with metastatic melanoma." (PMID 26204954, 2015). "Given the evidence in murine models that low PTEN and BRAF V600 mutations results in development of metastatic melanoma, we conducted an exploratory analysis based on PTEN mRNA expression and BRAF/NRAS status." (PMID 24830350, 2014). "We have analysed the NRAS and BRAF mutational status of a series of 44 early passage lines developed from New Zealand patients with metastatic melanoma." (PMID 23658559, 2013). "We have examined the utilisation of these three signalling pathways in a number of cell lines derived from patients with metastatic malignant melanoma of known PIK3CA, PTEN, NRAS and BRAF mutational status." (PMID 22475322, 2012). "It has also been demonstrated that levels of mutant BRAF and NRAS ctDNA concentrations in patients with metastatic melanoma correlated with decreased metabolic activity monitored by fluorodeoxyglucose positron emission tomography (FDG-PET) in response to therapeutic interventions." (PMID 39156972, 2024). "NRAS produces splice variants that are more immunogenic than canonical proteins encoded by the same gene with missense mutations, and the number of CD44 variants is further increased in metastatic melanoma." (PMID 38462618, 2024). "Although of interest, this study was focused on B16F10 mouse metastatic melanoma cell line, wild-type respect to either BRAF or NRAS mutations, and indicated the tumor microenvironment as key mediator of LY500307 effects, without evidence of any cell-dependent pathway activation." (PMID 35371312, 2022). "On the other hand, NRAS mutations slightly outnumbered BRAF mutations in undifferentiated metastatic melanoma with or without known primary." (PMID 33506327, 2021). "As yet, no cases of NRAS-mutated metastatic melanoma treated with MEK inhibitors have been published." (PMID 34071371, 2021). "Treatments of metastatic melanoma underwent an impressive development over the past few years, with the emergence of small molecule inhibitors targeting mutated proteins, such as BRAF, NRAS, or cKIT." (PMID 32455924, 2020). "Nevertheless, NRAS mutational status was described as a prognostic factor of shorter OS for stage IV non-uveal metastatic melanoma and primary invasive melanoma patients." (PMID 33072757, 2020). "In patients with unresectable advanced-stage metastatic melanoma, BRAF and NRAS mutations identified in ctDNA analysis at baseline and during treatment with targeted therapy against BRAF or immunotherapy have been associated with larger tumors, increased LDH levels, and brain metastases." (PMID 32010431, 2020). "Some authors reported that NRAS mutations are not prognostic factors for metastatic melanoma patients." (PMID 33072757, 2020).
metastatic melanoma (continued). "Although a high discordance rate of the BRAF p.V600E mutation has been reported in 8 (44%) of 18 paired primary and metastatic melanoma specimens, BRAF and NRAS mutations are generally highly concordant with variation of discordance rates depending on the metastatic sites in larger cohort studies." (PMID 31277584, 2019). "Several clinical trials have convincingly shown that immune checkpoint inhibitors increase the overall survival of metastatic melanoma patients with or without BRAF/NRAS mutations." (PMID 28231855, 2017). "However, all these studies were performed in the metastatic melanoma setting, and it is not possible to verify whether NRAS mutation at the Q61 site had a role in the rapid deterioration of clinical conditions observed in our two patients." (PMID 39148899, 2024). "In a subsequent dose expansion phase of the study, the safety and preliminary antitumor activity of tovorafenib were further evaluated in cohorts of patients with BRAF-mutant, NRAS-mutant and BRAF/NRAS wild-type metastatic melanoma." (PMID 37219686, 2023). "Genetic alterations in BRAF, NRAS and NF1 that activate the ERK cascade, account for over 80% of metastatic melanomas." (PMID 29180761, 2017). "NRAS-mutant metastatic melanoma is an aggressive and deadly disease with no effective second-line treatments." (PMID 36765910, 2023). "P62, an autophagy-degrading factor, is overexpressed in malignant and metastatic melanomas regardless of BRAF/NRAS mutant status." (PMID 36747120, 2023). "BRAF, NRAS, and NF1 mutational status in metastatic melanoma was not statistically associated with differences in either overall survival or progression-free survival, except for rare patients with BRAF fusions or internal BRAF gene rearrangements." (PMID 37444637, 2023). "Surprisingly, the published results for monitoring BRAF or NRAS mutant metastatic melanoma have not been adopted in routine clinical oncology." (PMID 30546839, 2018). "Outside of a clinical trial setting, ipilimumab is a feasible treatment option in patients with pretreated metastatic melanoma, regardless of BRAF and NRAS mutational status." (PMID 24885479, 2014). "The results suggest that ipilimumab is an effective and safe treatment for pretreated patients with metastatic melanoma regardless of BRAF and NRAS mutation status." (PMID 24885479, 2014). "CYT-high metastatic melanomas had recurrent copy number amplifications in loci 1p12 (NOTCH2), 1q44 (OR2M4), 7q36.1 (KCNH2), 11q13.3 (FGF3/4), 12p11.23 (MED21) and 12q13.3 (R3HDM2) and deletions in 1p22.1 (RHOC, NRAS), 9p21.3 (CDKN2B), 10q23.2 (miR346), 11q23.3 (ATM, CHEK1, ETS1) and 15q15.3 (CASC4)." (PMID 33779796, 2021). "We next performed immunohistochemical analysis of biopsies from 54 patients with genetically diverse metastatic melanoma and confirmed high expression of BRD4 in NRASMut tumors; BRD4 levels were markedly higher than in tumors harboring mutant BRAF or wild‐type for BRAF and NRAS (WT)." (PMID 29650805, 2018).
thyroid cancer (87 papers, 2012 to 2026). "There are fewer studies related to other genes with higher mutation frequencies such as NRAS in our findings, which found that NRAS mutations were linked to the high risk of distant metastasis of thyroid cancer." (PMID 40963858, 2025). "After BRAF, activating mutations of RAS (NRAS >> HRAS > KRAS) are the next most common oncogenic drivers found in advanced thyroid cancers." (PMID 39874138, 2025). "NRAS Q61R and Q61K mutations were more frequently observed in skin and thyroid cancers than in other cancer types." (PMID 40970755, 2025). "The tumor harbored a NRAS mutation and exhibited histological features consistent with poorly differentiated thyroid carcinoma, while serum Tg levels closely reflected tumor status." (PMID 41322887, 2025). "For example, CDKN2A and NRAS alterations, which were mutated in 8.1% and 11.3% of thyroid cancers respectively in Black patients, were more common in Black than White patients." (PMID 38297963, 2024). "Among the study population, nine patients harbored BRAF V600E mutations, three had NRAS mutations, and one patient had wild-type thyroid cancer." (PMID 39685478, 2024). "RAS mutated proteins (KRAS, HRAS, and NRAS) promote the uncontrolled growth of thyroid carcinoma cells, thereby contributing mostly to cancer initiation." (PMID 39519020, 2024). "Even so, FTCs displaying NRAS protein (one of the most common RAS mutated forms in thyroid cancer) are associated with a higher risk of metastasis." (PMID 39519020, 2024). "Of note, EIF1AX mutations were found almost exclusively in HRAS-, KRAS-, and NRAS-mutant thyroid cancers (p<0.05), whereas STK11 mutations were found in greater proportion of HRAS-mutant NSCLC compared to the other HRAS-mutant cancer types." (PMID 37503077, 2023). "Mutation in the NRAS gene was found to be more commonly harnessed to poorly differentiated thyroid carcinomas and anaplastic thyroid cancers than PTC." (PMID 38115146, 2023). "Regarding NRAS mutation, our results revealed a significantly increased expression of Furin in thyroid carcinomas wild-type for the NRAS mutation that were mostly Papillary Thyroid Carcinomas." (PMID 37568724, 2023). "In the thyroid cancer samples BRAF mutations co-occurred less frequently than expected with mutations in NRAS, HRAS, RET, PTEN, NF1 and KRAS." (PMID 36275468, 2022). "As a motivating example, other studies have shown that activating mutations in Ras isoforms (HRAS, KRAS, NRAS) tend to have similar effects to one another in thyroid cancer, producing similar gene expression signatures." (PMID 35761387, 2022). "Of 12 patients with increased radioiodine uptake, 5 out of 5 patients had NRAS-mutated thyroid cancer, while 4 of 9 patients had thyroid cancer with BRAF V600E mutation." (PMID 34944814, 2021). "In conclusion, aggressive variants of PTC had higher BRAF and lower NRAS mutation prevalence than other thyroid cancers." (PMID 33672707, 2021). "In adult thyroid cancer, NRAS codon 61 (NRAS Q61K) and HRAS codon 61 (HRAS Q61R) mutations are the most frequent." (PMID 33120984, 2020). "Activating NRAS exon 2, 3 or 4 mutations were described as relatively rare, but significant in thyroid carcinomas occuring in approx. 10% in total and associated with adverse prognosis." (PMID 30666518, 2019). "Among the RAS family members, NRAS mutations were also linked to levels of T cells and Tregs in thyroid cancer." (PMID 28749946, 2017). "The third-ranked gene, NRAS, encodes membrane-associated proteins that play a vital role in the transduction of signals, which has been reported in thyroid cancer." (PMID 28938536, 2017). "RAS (HRAS and NRAS) mutations are the second most common genetic alterations in thyroid cancers, which were mutually exclusive with BRAF mutations (the most common mutations in thyroid cancers)." (PMID 28582771, 2017). "The highly mutated genes (KRAS, HRAS, NRAS, etc.)in somatic cells of thyroid cancer were rarely observed to mutate in patients’ blood in our study." (PMID 26530882, 2015).
thyroid cancer (continued). "We conducted a subanalysis of 60 thyroid cancer patients to examine the clinicopathologic significance of NRAS mutation in thyroid cancer." (PMID 25254041, 2014). "We observed that most thyroid cancers positive for NRAS mutation were encapsulated FVPTC and 2 (15%) of 13 FTCs carried the mutation." (PMID 25254041, 2014). "The results of this study allow us to conclude that low expression of MLH1 is associated with BRAF V600E mutations, RET/PTC rearrangements and transitions (IDH1 and NRAS) in patients with thyroid carcinoma." (PMID 23414134, 2013). "NRAS mutation can be found in both thyroid adenoma and thyroid cancer." (PMID 40226091, 2025). "NRAS mutations were frequently observed in skin and thyroid cancers." (PMID 40970755, 2025). "NRAS Q61R is the most common NRAS pathogenic variant in thyroid cancer." (PMID 40226091, 2025). "In ovarii thyroid cancer, NRAS gene mutations may be associated with lymph node and distant metastasis." (PMID 36607876, 2023). "Thus higher frequency of RAS (HRAS and NRAS) mutations was observed in thyroid cancers with high-level energy metabolism because of high-frequency A→G mutations." (PMID 28582771, 2017). "A meta-analysis including 2552 thyroid cancer patients from 17 studies reported an overall RAS mutation prevalence of 35.4% (95% CI: 22.7–50.7%), with NRAS being the most frequent subtype (69.5%), followed by HRAS (25.8%) and KRAS (6.9%)." (PMID 41595518, 2026). "Oncogene-induced production of ROS promotes the initiation and progression of thyroid cancer by enhancing the activation of major signaling pathways triggered by oncogenes (NRAS, PTEN), forming a vicious cycle that propels its pathogenesis." (PMID 39180118, 2024). "Among the genes associated with thyroid cancer BRAF, RAS, KRAS, NRAS, PTEN, and PRKAR1A genes participate in regulating oxidative metabolism." (PMID 39180118, 2024). "Three patients had an NRAS mutation, two with FTC and one with a poorly differentiated thyroid carcinoma, and three patients had a BRAF V600E mutation and PTC." (PMID 39685478, 2024). "-The clinical utility of BRAF, KRAS, NRAS, and TERT promoter mutation analysis on ctDNA appeared to be limited to early-stage thyroid cancers." (PMID 37762070, 2023). "Two of the most important and common mutations found in thyroid cancer are BRAFV600E mutations and RAS-like mutations, which involve a family of three highly homologous isoforms (NRAS, KRAS and HRAS)." (PMID 35246262, 2022). "RAS mutations (including its variants, including NRAS, KRAS, and HRAS) are the most commonly mutated genes in thyroid cancer." (PMID 36613811, 2022). "The three isoforms of RAS (HRAS, NRAS, and KRAS) mutations are the second most common mutation encountered in thyroid carcinomas." (PMID 35197932, 2022). "The clinical utility of BRAF, KRAS, NRAS, and TERT promoter mutation analysis on ctDNA appears to be limited to early-stage thyroid cancers." (PMID 33915745, 2021). "Thirty-two somatic mutations were identified exclusively in known thyroid cancer genes (BRAF, KRAS, NRAS, and TERT)." (PMID 33821390, 2021). "Limited data are available on the diagnostic utility of circulating tumor DNA (ctDNA) in early-stage thyroid cancers for BRAF, KRAS, NRAS, and TERT promoter mutations, which are known detectable markers for thyroid cancers." (PMID 33915745, 2021). "In this study, 73 matched neoplastic tissue and plasma DNA samples and 54 plasma DNA samples from healthy individuals were examined for the diagnostic utility of ctDNA in thyroid cancers focusing on BRAF, KRAS, NRAS, and TERT promoter mutations." (PMID 33915745, 2021).